STC1 (stanniocalcin 1)
Diseases named in the same sentence as STC1 in open-access papers (continued):
Sharing a sentence is not in itself a finding about the gene and the disease.
nasopharyngeal carcinoma (4 papers, 2011 to 2020). A carcinoma arising from the nasopharyngeal epithelium.
Obesity (4 papers, 2017 to 2024). Accumulation of substantial excess body fat. "As STC-1 expression was particularly low in cases with obesity and DMT2 in the TMA cohort, we also evaluated the correlation between metformin use and STC-1 expression in an additional EC cohort that only included women with DMT2 (n = 111)." (PMID 34650342, 2021). "Furthermore, weak STC1 expression was also observed in women with obesity and type 2 diabetes mellitus who also had EnCa." (PMID 39186548, 2024). "However, elevated expression of STC1 presented in women with obesity or overweight compared with those with a lower BMI, suggesting that obesity may be a stress factor that leads to the induction of endometrial STC1 expression." (PMID 39186548, 2024). "However, our findings presented herein suggested that STC-1 and STC-5 may be promising novel compounds for the treatment of obesity and related diseases." (PMID 28417922, 2017). "Despite a 3-month lifestyle intervention, commonly recommended as the first-line therapy for women with PCOS and obesity, STC1 expression in the PCOS endometrium remained unchanged, suggesting impaired regulation of STC1 in PCOS regardless of BMI." (PMID 39186548, 2024).
oral squamous cell carcinoma (4 papers, 2022 to 2026). "Impressively, lysates obtained from oral squamous cell carcinoma lines HSC2 and TR146 but also the healthy equivalent, the oral epithelial cells, all provoked the increased expression of STC1, AREG, and C11orf96 in gingival fibroblasts." (PMID 39061769, 2024).
preeclampsia (4 papers, 2012 to 2024). Preeclampsia is a hypertensive disorder of pregnancy that is characterized by new-onset hypertension with proteinuria presenting after 20 weeks of gestation, and depending on mild or severe forms may initially present with severe headache, visual disturbances, and hyperreflexia. "Additionally, genetic research has confirmed the associations between specific STC1 gene variants and maternal hormone levels, with implications for the development of late-onset preeclampsia." (PMID 39186548, 2024). "We were further able to demonstrate a significant difference in the circulating concentration of STC‐1 in the women with preeclampsia compared to normal pregnancies." (PMID 32162740, 2020). "Stanniocalcin‐1 (STC‐1) is a multi‐functional glycosylated peptide present in the plasma of healthy women postpartum and increased further in pregnancies complicated by preeclampsia." (PMID 32162740, 2020). "Further underlining its importance in renal homeostasis, we report significant increase in placental STC1 expression and in maternal post-partum plasma STC1 in preeclampsia, known to be accompanied by impaired renal function." (PMID 23145134, 2012). "Moreover, the increased STC1 expression in patients with preeclampsia raises questions about the relevance of placental genes in disease progression and points to a possible function for STC1 as a biomarker of pregnancy complications." (PMID 39186548, 2024). "We have focused on STC‐1, a little studied hormone, which in health is only detectable in the circulation during pregnancy and is further elevated in pregnancies complicated by preeclampsia." (PMID 32162740, 2020). "Interestingly, a clinical study discovered significantly higher STC1 levels in the plasma of women with preeclampsia than in those without the condition." (PMID 39186548, 2024).
acute leukemia (3 papers, 2013 to 2023). A clonal (malignant) hematopoietic disorder with an acute onset, affecting the bone marrow and the peripheral blood. "For acute leukemia, a relation between the expression level of STC‐1 mRNA in peripheral blood and recurrence after chemotherapy has been suggested." (PMID 33826244, 2021).
acute myeloid leukemia (3 papers, 2020 to 2024). Acute myeloid leukemia (AML) is a group of neoplasms arising from precursor cells committed to the myeloid cell-line differentiation. "STC1 is found at elevated levels in the peripheral blood and bone marrow in acute myeloid leukemia." (PMID 33668652, 2021).
dementia (3 papers, 2020 to 2024). Loss of intellectual abilities interfering with an individual's social and occupational functions. "Research found that STC-1 in the CSF can be used as a biomarker for the differential diagnosis of dementia." (PMID 33132863, 2020).
kidney failure (3 papers, 2015 to 2025). An acute or chronic condition that is characterized by the inability of the kidneys to adequately filter the blood. "Instead, nephrotoxic nephritis following kidney-specific knockdown of STC1 was associated with glomerular necrosis/hyalinosis, severe tubular epithelial injury and sloughing, massive cast formation, and kidney failure." (PMID 26393521, 2015). "Consistent results were observed after kidney or endothelial cell-specific knockdown of STC1, which resulted in greater generation of superoxide, cell apoptosis, and kidney failure." (PMID 41249792, 2025). "Notwithstanding the proximal tubular injury and moderate kidney failure that we expected after knockdown of STC1 in the kidney, absence of STC1 was expected to promote inflammation after nephrotoxic nephritis." (PMID 26393521, 2015).
laryngeal squamous cell carcinoma (3 papers, 2014 to 2025). A squamous cell carcinoma that arises from the larynx. "And STC1 is significantly overexpressed in laryngeal squamous cell carcinoma." (PMID 39012409, 2024). "In studies of laryngeal squamous cell carcinoma (LSCC), STC1 has been shown to regulate the M2 polarization of TAMs and modulate immune cell function through metabolic reprogramming." (PMID 40741411, 2025). "The roles of STC1 and STC2 in laryngeal squamous cell carcinoma (LSCC) remain unknown." (PMID 24743310, 2014).
liver cancer (3 papers, 2021 to 2023). An epithelial or non-epithelial malignant neoplasm that arises from the liver. "We measured the concentration of STC1 in the serum of patients with advanced liver cancer (n = 17) and patients with early liver cancer (n = 42) by ELISA." (PMID 37004088, 2023). "Furthermore, ELISA revealed that the serum STC1 concentration was higher in patients with advanced liver cancer than in patients with early liver cancer." (PMID 37004088, 2023). "Patients with advanced liver cancer possessed higher serum STC1 concentrations than patients with early liver cancer, suggesting that STC1 could be a biomarker for poor prognosis in HCC." (PMID 37004088, 2023).
osteoarthritis (3 papers, 2020 to 2021). A noninflammatory degenerative joint disease occurring chiefly in older persons, characterized by degeneration of the articular cartilage, hypertrophy of bone at the margins and changes in the synovial membrane. "And recent research has reported that upregulation of stanniocalcin-1 can inhibit the development of osteoarthritis, but to our best knowledge, there is still no study that has reported the correlation between STC and IDD by miRNA regulation." (PMID 34650661, 2021).
pancreatic cancer (3 papers, 2022 to 2025). "Hypoxia-inducible factor-α promotes STC1 expression and subsequent PI3K/AKT downstream activation leading to pancreatic cancer chemoresistance in preclinical models." (PMID 39807836, 2025).
pancreatic ductal adenocarcinoma (3 papers, 2023 to 2025). An infiltrating adenocarcinoma that arises from the epithelial cells of the pancreas. "STC1 has also been reported to be associated with gemcitabine resistance in pancreatic ductal adenocarcinoma." (PMID 39807836, 2025).
retinal degeneration (3 papers, 2021 to 2022). Degeneration of the retina. "Our results showed that Stc1 and Stc2 were highly expressed in the retina of wild type mice and their expression was largely unaffected by the loss of photoreceptors during retinal degeneration." (PMID 35812222, 2022). "One group studied the effects of an AAV vector encoding STC-1 (AAV-STC-1) in two transgenic mice models of retinal degeneration (P23H-1 and S334ter-4)." (PMID 33920974, 2021). "Hence, it would be interesting to investigate how Stc1–/– and Stc2–/– mice respond when subjected to hypoxic stress or to photoreceptor loss in models of retinal degeneration." (PMID 35812222, 2022). "To investigate whether expression of Stc1 and Stc2 is affected by retinal degeneration, we analyzed their mRNA levels in rd10 mice that are characterized by a progressive loss of rod photoreceptors starting around PND15 and a loss of almost all photoreceptors at 6 months of age." (PMID 35812222, 2022). "However, STC1 increased cell viability of the retinal cell line RGC-5 and rescued retinal degeneration in two rat models after intravitreal protein injection or AAV-mediated gene delivery." (PMID 35812222, 2022).
acute kidney injury (2 papers, 2020). Sudden and sustained deterioration of the kidney function characterized by decreased glomerular filtration rate, increased serum creatinine or oliguria. "The results of this study present that the STC1-Nrf2 pathway contributes to resisting contrast medium-induced acute kidney injury through downregulating mitochondrial damage, suppressing oxidant stress, and inhibiting inflammation and apoptosis in the kidney." (PMID 32318235, 2020).
atherosclerosis (2 papers, 2024). A disease characterized by the build-up of fatty material and calcium deposition in the arterial wall resulting in partial or complete occlusion of the arterial lumen. "Notably, these correlations might suggest a link between the metabolome and protein markers related to immune signalling (LTα, CD6, CCL21, SELE), energy balance and metabolism-related hormones (IGFBP1, SHGB, ADM, leptin, and STC1), and atherosclerosis/thrombosis inhibitor (PAI1)." (PMID 39154540, 2024). "A similar expression pattern is visible in other inflammation and atherosclerosis related genes such as APOE, KLF4, CXC3L1, STC1, CH25H, and ABCG1." (PMID 39695567, 2024).
breast tumor (2 papers, 2020 to 2023). "However, there is also evidence indicating that STC1 can significantly promote breast tumor growth." (PMID 37400459, 2023). "Moreover, we implanted the MDA-MB-231 cells into the mammary fat pads of BALB/c nude mice and found that STC1 had no impact on the growth of primary breast tumors." (PMID 37400459, 2023). "Triple‐negative breast cancer (TNBC) tends to have a very high STC1 level compared to normal tissues, and ER‐positive tumours also possess a relatively higher STC1 expression level than normal, whereas STC1 may be absent in BRCA1‐mutant breast tumours." (PMID 32468698, 2020). "Welcsh et al53 described the absence of BRCA1 expression in primary breast tumour cells without expression of STC1 and that BRCA‐1‐induced cells had a much higher expression level of STC1 compared with control cells." (PMID 32468698, 2020).
chronic kidney disease (2 papers, 2012 to 2021). Impairment of the renal function secondary to chronic kidney damage persisting for three or more months. "STC1 has been identified as one of the chronic kidney disease genes by genome-wide association studies (Böger and Heid, 2011)." (PMID 33898465, 2021).
colon adenocarcinoma (2 papers, 2022 to 2024). "The ceRNA axis MIAT/miR-532-3p/STC1 could serve as a promising therapeutic target for colon adenocarcinoma." (PMID 35607443, 2022).
depression (2 papers, 2021 to 2024). "Some DEGs linked to depression and neuroinflammation (BDNF, CCL2 (Curzytek and Leśkiewicz, 2021), STC1, MEF2C) were also downregulated in Cit200 over time." (PMID 39055655, 2024). "Taken together, STC1 was under-expressed and the ROS/NF-κB signaling pathway was activated in the rat model of depression-like behaviors." (PMID 34194345, 2021). "Our study demonstrated that STC1 elevated the numbers of BrdU- and Nestin-positive cells in rats with depression-like behaviors, suggestive of its beneficial role in neurogenesis." (PMID 34194345, 2021). "Also, STC1 has been shown to decrease neuroinflammation and attenuate depression-like symptoms in rats." (PMID 39055655, 2024). "Finally, the effects of STC1-mediated ROS/NF-κB signaling pathway on the depression-like symptoms in vivo." (PMID 34194345, 2021). "In addition to these effects, STC1 exert suppressive effect on inflammation and promotive effect on neural plasticity in the rats with depression-like behaviors." (PMID 34194345, 2021). "Our findings suggested that the anti-inflammatory role of STC1 and its neuroprotective in depression-like behaviors might be achieved by mediation on the ROS/NF-κB signaling pathway." (PMID 34194345, 2021). "Hence, we further analyzed whether STC1 could mediate the ROS/NF-κB signaling pathway in rats with depression-like behaviors." (PMID 34194345, 2021). "We conducted this study with an aim to explore the effect of stanniocalcin-1 (STC1) on inflammation and neuron injury in rats with depression-like behaviors." (PMID 34194345, 2021). "Furthermore, overexpression of STC1 resulted in enhanced neural plasticity, reduced release of pro-inflammatory proteins, elevated SOD and CAT and diminished MDA level in the hippocampus of rats with depression-like behaviors." (PMID 34194345, 2021).
endometriosis (2 papers, 2022 to 2024). The growth of functional endometrial tissue in anatomic sites outside the uterine body. "Conversely, the reduced STC1 level in eSCs may indicate a possible decidualization defect in women with endometriosis." (PMID 39186548, 2024). "In patients with endometriosis, STC1 is upregulated in the mid-secretary eutopic endometrium." (PMID 36171908, 2022). "In addition, the upregulation of the STC1 protein in endometrial fluid in the secretory phase compared with the proliferative phase has been observed in healthy women compared with women with endometriosis." (PMID 39186548, 2024). "In in vitro experiments, eSCs treated with cAMP, known as an inducer of STC-1 expression, demonstrate dramatically upregulated STC1 expression in healthy eSCs but to a lesser extent in eSCs from women with endometriosis, possibly via PKA pathways." (PMID 39186548, 2024). "Of note, STC1 expression is not significantly affected in eSCs decidualized with E2 and P4 in either the healthy or endometriosis group, suggesting that sex steroids do not regulate endometrial STC1 expression, consistent with findings from the equine endometrium." (PMID 39186548, 2024). "The high abundance of STC1 in the secretome of the receptive endometrium from women without endometriosis may indicate a greater likelihood of successful implantation." (PMID 39186548, 2024).
esophageal cancer (2 papers, 2012 to 2024). A primary or metastatic malignant neoplasm involving the esophagus. "Table I shows the correlation between STC1 expression detected by immunohistochemistry and various clinicopathological parameters in 229 patients with esophageal cancer." (PMID 22200953, 2012). "Using quantitative RT-PCR, the STC1 mRNA expression level increased in a time-dependent manner in esophageal cancer cells (TE8) cultured under hypoxia; and at 48 h, the expression level was 1000 times that under normoxia." (PMID 22200953, 2012). "The results showed marked induction of STC1 expression under hypoxia in cultured cells and in esophageal cancer cells and that overexpression of STC1 was an independent prognostic factor in patients with esophageal cancer who had undergone curative surgery." (PMID 22200953, 2012). "Furthermore, examination of STC1 expression in 229 cases with esophageal cancer by immunohistochemistry, showed positive staining in 89 cases (38.9%), at least in part of the tumor, and the staining was mainly localized in the cytoplasm of tumor cells." (PMID 22200953, 2012). "Further studies are needed to elucidate the exact roles of STC1 and STC2 in hypoxia and in progression of esophageal cancer." (PMID 22200953, 2012). "Although evidence points to the role of STC1 in human cancers, the clinical significance of STC1 expression in esophageal cancer has not been well established." (PMID 22200953, 2012).
fibrosarcoma (2 papers, 2005 to 2022). A malignant mesenchymal fibroblastic neoplasm affecting the soft tissue and bone. "STC1 is related to diseases such as fibrosarcoma and participates in ectodermal differentiation." (PMID 35361159, 2022). "Both STC1 and STC2 are reported to be secreted as phosphoproteins from human fibrosarcoma, a tumor of mesenchymal cells." (PMID 16343351, 2005).
gastric adenocarcinoma (2 papers, 2024). "STC1 (Stanniocalcin 1) is a protein that is highly expressed in gastric adenocarcinoma." (PMID 38752750, 2024). "In summary, molecules such as DKK1, GHRL, STC1, NRP1 and ITGAV play important roles in the development and prognosis of gastric adenocarcinoma." (PMID 38752750, 2024).
head and neck squamous cell carcinoma (2 papers, 2023 to 2024). A squamous cell carcinoma that arises from any of the following anatomic sites: lip and oral cavity, nasal cavity, paranasal sinuses, pharynx, larynx, and salivary glands. "Targeting six immune-related genes (CXCL5, ADM, FGF9, AIMP1, STC1, and CDKN2A) in individuals diagnosed with head and neck squamous cell carcinoma has shown promising results in immunotherapy triggered by periodontal disease." (PMID 37675228, 2023).
Hepatitis (2 papers, 2019 to 2021). Inflammation of the liver. "The effect of stanniocalcin 1 secreted from SHED-Heps is anti-hepatitis." (PMID 33436050, 2021). "Transplantation of STC1-siRNA treated SHED-Heps in fulminant LEC rats negatively regulated the SHED-Hep-transplantation-mediated anti-oxidative and anti- hepatitis effects in the recipient livers." (PMID 30733544, 2019).
infertile (2 papers, 2024). "It has been shown that stanniocalcin-1, a protein negatively affecting implantation, is increased in polyps diagnosed in infertile women." (PMID 39200896, 2024).
lymphoma (2 papers, 2022 to 2023). A malignant (clonal) proliferation of B- lymphocytes or T- lymphocytes which involves the lymph nodes, bone marrow and/or extranodal sites. "By modulating TME, MSCs showed a strong suppressive function on CAR-T efficacy toward lymphoma cells, and interestingly, the presence of the STC1 gene played a critical role." (PMID 36779699, 2023).
malignant glioma (2 papers, 2020 to 2022). A grade III or grade IV glioma arising from the central nervous system. "The presence of regional STC1 uncouples the oxidative phosphorylation process by increasing the expressions of mitochondrial UCP2, which is a valuable biomarker for the diagnosis of malignant glioma for the assessment of postoperative prognosis." (PMID 36713509, 2022).